INS (insulin)
Diseases named in the same sentence as INS in open-access papers (continued):
Sharing a sentence is not in itself a finding about the gene and the disease.
Hypoglycemia (continued). "Another possible explanation is that patients avert the risk of hypoglycemia before physical activity by underdosing insulin or by injecting carbohydrate, and this offsets the benefits of exercise." (PMID 23935617, 2013). "This was seen in this study for subjects on background therapy with insulin or a sulphonylurea agent, in whom both canagliflozin doses were associated with the expected higher incidences of hypoglycaemia relative to placebo." (PMID 23464594, 2013). "Adjustment of insulin doses is an important factor in maintaining optimized glycaemic control while minimizing the risk of hypoglycaemia." (PMID 22998363, 2013). "Adult patients who live alone or have occupations which preclude a degree of risk of hypoglycemia, for example, the elderly, taxi drivers and sportsmen, should avoid insulin, SUs and glinides and favor metformin and DPP-4 inhibitors." (PMID 23841986, 2013). "The use of rapid-acting insulin analogues for the mealtime bolus, which when combined with intermediate-acting insulin, can reduce the risk of hypoglycemia and the need for snacks between meals." (PMID 24011173, 2013). "An ideal basal insulin for children and adolescents would provide a physiological, flexible, and predictable profile, with a low risk of hypoglycemia." (PMID 23448369, 2013). "Identified in two Finnish families, exercise-induced hyperinsulinism (EIHI) is characterized by episodes of hypoglycemia associated with elevated insulin levels at the time of anaerobic exercise." (PMID 23384201, 2013). "On the other hand, the use of sulfonylureas in patients treated with insulin is questionable, as it increases the risk of hypoglycemia, whereas thiazolidinediones are associated with a higher risk of heart failure when combined with insulin." (PMID 24348585, 2013). "In conclusion, NICTH should be considered in patients who present with recurrent hypoglycemia associated with suppressed serum insulin and IGF1 levels." (PMID 24616774, 2013). "Although exogenous insulin therapy improves glycemic control, it carries the risk of hypoglycemia and can be cost-prohibitive." (PMID 23554999, 2013). "Because S43126 increased insulin release at higher glucose levels compared to basal condition, the risk of hypoglycemia associated with the use of S43126 is diminished." (PMID 27429837, 2012). "There is a need for insulin regimens that are less restrictive and burdensome with lower risk of hypoglycaemia." (PMID 22313123, 2012). "In Hirata's disease insulin autoantibodies are detected in association with hypoglycemia in the patient." (PMID 22567309, 2012). "Biochemical studies confirmed endogenous pancreatogenous insulin secretion as the cause of episodic hypoglycemia, but imaging studies and selective arterial calcium stimulation failed to localize an insulinoma." (PMID 22937294, 2012). "High levels of circulating insulin coupled with the observed variability in insulin sensitivity result in increased glycemic variability and an increased risk of hypoglycemia during the first 24 hours of ICU stay." (PMID 22703645, 2012). "An ideal regimen would minimize the number of injections required, the risk of hypoglycaemia and the consequences of a delayed or missed insulin dose." (PMID 22313123, 2012). "The risk of hypoglycemia is often cited as a barrier to large-scale adoption of glycemic control by insulin infusions, especially as most neonatal hypoglycemia appears to be asymptomatic." (PMID 22871230, 2012). "Surprisingly, they found the seemingly the opposite phenotype on their TCF7L2 null allele compared with our results, in that the TCF7L2 knockout mice displayed hypoglycemia that was associated with reduced plasma insulin levels." (PMID 23028378, 2012). "Firstly, most studies comparing the effects of human insulin with those of insulin analogues specifically exclude patients at risk of severe hypoglycaemia, such as patients with previous severe events or impaired hypoglycaemia awareness, from participation." (PMID 22727048, 2012).
Hypoglycemia (continued). "Again, intensive insulin therapy reduced morning blood glucose levels at the expense of a significantly greater risk of hypoglycaemia." (PMID 22998112, 2012). "Congestive heart failure is associated with hypoglycemia because of decreasing insulin clearance and severe liver dysfunction, which inhibits glucose release from liver cells." (PMID 23198181, 2012). "Increased measurement frequency, higher target glycemic bands, conservative insulin dosing, and modulation of carbohydrate nutrition should be considered to minimize safely the outcome glycemic variability and reduce the risk of hypoglycemia." (PMID 22703645, 2012). "Insulinoma is characterized by a prevailing and inappropriate secretion of insulin that causes a syndrome of hypoglycemia (100%), neuroglycopenic symptoms (80–100%), and symptoms of adrenergic stimulation (80–100%)." (PMID 24213321, 2012). "Greater variability with lower SI early in a patient’s stay greatly increases the insulin required, potential glucose flux due to variation in SI, and thus the risk of greater glycemic variability and hypoglycemia." (PMID 22703645, 2012). "The revision added cautions about an increased risk of hypoglycemia when combining the use of sitagliptin with an SU or insulin and suggested lowering the dose of the SU or insulin." (PMID 24300302, 2012). "Although the mechanism for this finding is not clear, it is possible that the insulin sensitizing action of the TZD accentuates the risk of hypoglycemia of insulin when these two are used in combination." (PMID 22646230, 2012). "The principal practical challenge in adding exenatide twice-daily therapy for patients already on basal insulin is the risk of hypoglycaemia, coupled with minimal knowledge regarding home glucose levels." (PMID 23061886, 2012). "Since the cleaving agent is endogenous glucose itself, the amount of insulin released is directly dependent on the blood glucose concentration and is halted soon after reaching normoglycemia, thereby avoiding the risk of hypoglycemia." (PMID 22272238, 2012). "In high doses, glucagon can cause paradoxical insulin secretion, implying that infants receiving glucagon bolus should receive intravenous glucose infusion to prevent rebound hypoglycaemia." (PMID 23032149, 2012). "Comparisons among insulin regimens and their association with cardiovascular health outcomes, hypoglycemia, health care utilization and costs will also be studied." (PMID 22999494, 2012). "In clinical practice, insulin treatment needs to be highly individualized in terms of doses and regiment in order to reach a balance between good glycemic control and the risk of hypoglycemia." (PMID 22720003, 2012). "In fact, short-acting analogues, with a faster action than regular human insulin, warrant a more accurate control of postprandial peak glucose, with lower risk of hypoglycemia." (PMID 23209929, 2012). "The use of animal models in this respect is limited by the fact that prolonged treatment with high doses of long-acting insulin formulations is associated with an elevated mortality for hypoglycemia." (PMID 23209929, 2012). "An additional study found that rats receiving the KD were also resistant to the loss of cortical neurons during insulin-induced hypoglycaemia." (PMID 24600621, 2012). "Metformin XR 500 mg was included in HDS (it had been ceased during admission) with new dose of insulin correct, therefore putting patient at risk of hypoglycaemia." (PMID 23228183, 2012). "For example, the type of treatment (diet and/or insulin), frequency and intensity of physical activity, and the risk of hypoglycemia." (PMID 23259688, 2012). "Despite improvements in the administration of insulin delivery and insulin supplying devices, maintenance of adequate and steady glucose levels with exogenous insulin therapy alone can be challenging and can cause episodes of hypoglycemia." (PMID 22675353, 2012).
Hypoglycemia (continued). "Maternal plasma glucose and insulin were unaltered by malaria; the result contrasts with a previous study in pregnant women with acute malaria, who had hypoglycaemia associated with increased glucose turnover, attributed to enhanced pancreatic β-cell function." (PMID 22429464, 2012). "HH is an important cause of hypoglycaemia in childhood caused by unregulated insulin secretion by β-cells." (PMID 23032149, 2012). "Morbidity and mortality were significantly reduced but intensified insulin therapy reduced morning blood glucose levels at the expense of a substantially greater risk of hypoglycaemia." (PMID 22998112, 2012). "This suggests that the use of insulin will increase the risk of hypoglycemia, unless variability in sensitivity to insulin is explicitly taken into account." (PMID 22871230, 2012). "They stated that hypoglycemia is highly prevalent and underrecognized in older people and that longer-acting sulfonylureas (or insulin) confer an increased risk." (PMID 23039216, 2012). "Agents that stimulate robust insulin secretion at basal levels of glucose are more likely to cause hypoglycemia in patients." (PMID 27429837, 2012). "One major drawback of intensive insulin therapy is the increased risk of recurrent hypoglycemia (RH)." (PMID 24403983, 2012). "The risk of hypoglycemia is a major concern for translation into human, while mice are quite resistant to insulin-induced hypoglycemia, possibly due to stronger counter-regulatory hormone responses." (PMID 21647401, 2011). "As the effects of GLP-1 on insulin and glucagon are glucose-dependent the risk of hypoglycaemia with its administration is low." (PMID 21255422, 2011). "Specific CIs that triggered such changes include hypoglycemia associated with intravenous insulin administration and the dislodgement of central lines because of insufficient fixation." (PMID 21958492, 2011). "• The effects of GLP-1 on insulin and glucagon are glucose-dependent, therefore, the risk of hypoglycaemia with its administration is low." (PMID 21255422, 2011). "As for neurohumoral responses to insulin-induced hypoglycemia, diminution of GK and loss of BAD have divergent effects." (PMID 22162752, 2011). "Patients on insulin are at particularly high risk for hypoglycaemia compared to patients on oral antidiabetic drug therapy." (PMID 21756359, 2011). "Sliding scale insulin use has been associated with severe hypoglycemia, particularly in patients who are very sensitive to insulin and, if prescribed, should be used with extreme caution." (PMID 23882328, 2011). "Although effective in reducing the risk of hypoglycemia, glucagon cannot be fully relied upon to reverse the effect of insulin overdelivery." (PMID 22071283, 2011). "Overall, these results indicate BAD deficiency is associated with impaired counterregulatory responses to insulin-induced hypoglycemia, a clinically relevant glucoprivic threat." (PMID 22162752, 2011). "Intensification of insulin therapy has become an essential treatment method, but it has been hindered by an increased risk of hypoglycemia." (PMID 22071283, 2011). "Biphasic insulin analogues are associated with a lower incidence of nocturnal hypoglycaemia compared with human biphasic preparations and allow for intensification from once to twice or thrice daily dosing." (PMID 21410860, 2011). "During the past decades, long-acting insulin preparations have become widely used as a basal insulin supplement for diabetic patients due to their stable action and lower risk of nocturnal hypoglycemia." (PMID 21738645, 2011). "We planned to use the minimal model to assess insulin sensitivity, but decided against using insulin augmentation owing to risk of hypoglycemia in these young subjects." (PMID 21364957, 2011). "The concomitant insulin concentration should also be evaluated, to exclude hyperinsulinism as a cause of hypoglycemia." (PMID 22028893, 2011).
Hypoglycemia (continued). "Rapid delivery of sugars/carbohydrates into the duodenum result in rising blood sugar levels which then cause an extreme serum insulin response with subsequent rebound hypoglycemia." (PMID 21929798, 2011). "Simple sugars induce high insulin, and when used before exercise, this can lower the blood sugar and elicit the fatigue as well as lightheadedness associated with hypoglycemia." (PMID 21892942, 2011). "CCDSSs for insulin dosing generally kept glucose levels better in the target range, with an inconsistent lower risk for hypoglycaemia." (PMID 21824384, 2011). "This simulator is able to predict how glycated hemoglobin and risk of hypoglycemia evolves when the various doses of insulin and oral antidiabetics are increased or decreased." (PMID 20509903, 2010). "With many antidiabetic drugs such as sulfonylureas or insulin intensified blood glucose lowering has been associated with an increase in the rate of severe hypoglycemia." (PMID 20843379, 2010). "Physicians as well as patients fear the complexity of insulin regimes, the risk of hypoglycemia, and the chances of weight gain, as well as the necessity of a needle prick, with insulin therapy." (PMID 21059246, 2010). "These were caused by excessive hyper- or hypoglycemia, and all of them were treated by adjusting insulin dosages." (PMID 21234414, 2010). "Insulin itself and other antidiabetic drugs which produce their action by increasing the secretion of insulin, can cause dangerous hypoglycemia." (PMID 20582183, 2010). "The results showed that GLP-1 agonists are effective in improving glycaemic control and promoting weight loss, with a low risk of hypoglycaemia, and can be an alternative to immediate insulin in patients failing on combined oral glucose lowering agents." (PMID 21143938, 2010). "The risk of severe hypoglycaemia can be minimised by appropriate self-monitoring of blood glucose, regular review of insulin regimen, review of the quantity and timing of carbohydrate intake, and the use of CSII." (PMID 20633252, 2010). "Despite the essential role of insulin in the management of patients with insulin deficiency, insulin use can lead to adverse effects such as hypoglycaemia and weight gain." (PMID 21274337, 2010). "It is known that these drugs increase both basal insulinemia as insulin secretion stimulated by food ingestion, leading to weight gain and higher risk of hypoglycemia." (PMID 20718958, 2010). "The action of GLP-1 on β-cell receptors enhances insulin secretion in a glucose-dependant manner, which, in turn, minimises the risk of hypoglycaemia." (PMID 27713278, 2010). "Combination therapies, such as a sulfonylurea with insulin, are known to be associated with an increased risk for hypoglycemia and appear to have been used routinely in this study." (PMID 20843379, 2010). "Of the other dimensions, weak SOC was also associated with the hypoglycaemia-factor, that amongst other items contained questions about fear of hypoglycaemia and satisfaction with the current insulin regimen." (PMID 21110902, 2010). "The rapid acting insulin analogs, such as insulin aspart and lispro are safe during pregnancy, leading to better postprandial glycemic levels and causing less hypoglycemia (B)." (PMID 20416099, 2010). "Sulfonilureas (e.g., glibenclamida, glicazida, glimepiride) act by increasing both basal and meal-stimulated insulin secretion these obsviously carry the side effects of increasing weight gain and risk of hypoglycemia." (PMID 20718958, 2010). "One problem is that exogenous insulin injection reduces blood glucose and lead to hypoglycaemia that is associated with impaired memory." (PMID 20868513, 2010). "The two analogues were associated with comparable hypoglycaemia risks and variabilities, but insulin detemir therapy was associated with less weight gain." (PMID 20618882, 2010).
Hypoglycemia (continued). "Previous reports shows that insulin-induced hypoglycemia in normothermic rats caused progressive neurological depression and differentially altered regional cerebral acetylcholine metabolism." (PMID 20137086, 2010). "With particular attention to timely measurement and adjustment of insulin doses the risk of hypoglycemia experienced can be minimized." (PMID 19822000, 2009). "The results also indicate that a higher acute insulin response was associated with more prominent late hypoglycaemia, feeling of hunger and an increase in plasma ghrelin, respectively." (PMID 19781071, 2009). "For this reason, treatment with insulin is widely used; however, insulin therapy is associated with a substantial risk of hypoglycaemia, which is associated with both short- and long-term adverse events." (PMID 19439067, 2009). "After eliminating this study from the analysis, there remained moderate heterogeneity (I2 = 57%, p = 0.05) and there was significantly more hypoglycaemia in the pioglitazone plus insulin groups (relative risk 1.40, 95% CI: 1.14, 1.73, p = 0.002)." (PMID 19568428, 2009). "This benefit is projected despite the additional hypoglycaemia risk individuals who immediately initiated insulin would experience in the first 8 years of the simulation versus those with delayed initiation (570 events per 100 patient years)." (PMID 19804622, 2009). "Growth hormone stimulatory tests were made and insulin provocative test revealed a severe GH deficiency in this patient, defined by a peak response to insulin-induced hypoglycemia less than 3 ng/dl and IGF1 concentrations less than -2SDS." (PMID 19128470, 2009). "• Computerized IV insulin dosing can achieve and maintain glycemic control in critically ill patients with low risk of hypoglycemia when BG measurements are performed frequently and on time, thereby facilitating timely insulin dose adjustment." (PMID 19822000, 2009). "A low insulin incremental peak was associated with less severe late post-prandial hypoglycaemia (r = 0.38, p < 0.001), and hypoglycaemia was negatively correlated to subjective satiety at 180 min (r = -0.28, p < 0.05)." (PMID 19781071, 2009). "An updated meta-analysis that included the NICE-SUGAR results again found a six-fold increased risk of severe hypoglycemia among patients given intensive insulin therapy compared with controls, with little examination of the protocols represented." (PMID 19822000, 2009). "Observational data and findings from randomized trials have shown that TGC with insulin therapy also represents an independent risk factor for hypoglycemia." (PMID 19534781, 2009). "In fact, continuous exogenous insulin (pellets) more frequently caused hypoglycemia in diabetic NOD in the first few days after treatment, and rarely in EAD mice (data not shown)." (PMID 19287497, 2009). "Combination therapy is often associated with an increased risk for hypoglycaemia, particularly combinations that use sulphonylureas or insulin." (PMID 19614786, 2009). "Insulin provocative test revealed a severe GH deficiency in these patients, defined by a peak response to insulin-induced hypoglycemia less than 3 ng/dl and IGF1 concentrations less than – 2SDS." (PMID 19128470, 2009). "We found a severe GH deficiency, defined by a peak response to insulin-induced hypoglycemia less than 3 ng/dL and IGF1 concentrations less than -2SDS." (PMID 19128470, 2009). "Our data would further argue that while the occurrence of severe hypoglycemia is a known risk associated with IV insulin, especially with lower glucose targets, the risk is likely compounded with any protocol that can be difficult to use with consistency." (PMID 19822000, 2009). "This is largely because insulin cannot be used orally and insulin injections are associated with the risk of hypoglycemia and impairment of hepatic and other body functions." (PMID 21264157, 2008).